IL2 (interleukin 2)
Diseases named in the same sentence as IL2 in open-access papers (continued):
Sharing a sentence is not in itself a finding about the gene and the disease.
myocarditis (21 papers, 2012 to 2025). Myocarditis is a condition that is characterized by inflammation of the heart muscle (myocardium). "Approval for cancer immunotherapy has been granted to cytokines, such as IL-2, which have anticancer properties; however, they are also rare causes of myocarditis, occurring in 1.5% of 652 cases." (PMID 37941006, 2023). "Currently, there are no established biomarkers that would be helpful in predicting the risk of IL-2 related myocarditis." (PMID 35741162, 2022). "IL-2 implicated in myocarditis, and IL-4, IL-6, and IL-13 implicated in fibrosis and cardiomyopathy are the other inflammatory interleukins suppressed by NP-6A4." (PMID 34220518, 2021). "Nonetheless, it is plausible that the underlying mechanism is because of myocarditis given that in vivo half-life of IL-2 is approximately 5 to 7 minutes, and our patient’s ventricular arrhythmia occurred more than 12 days after her last IL-2 infusion." (PMID 29399586, 2018). "It expands the infiltration and accumulation of CD4+ and CD8+ T cells in the myocardium and promotes the release of myocarditis factors (such as IL-2, IL-6, etc.)." (PMID 36186992, 2022). "The current study shows that myocarditis is ubiquitous following IL-2 therapy, and that symptoms are a poor guide of the severity of the myocardial injury." (PMID 35741162, 2022). "The clinical approach to IL-2 related myocarditis is mainly supportive and includes termination of IL-2 therapy." (PMID 35741162, 2022). "The current study demonstrates that at approximately 3 months following IL-2 therapy, the acute myocardial inflammation has resolved and LV EF and QT interval have normalised." (PMID 35741162, 2022). "Clinically evident myocarditis following IL-2 therapy is also considered a contraindication to future therapy." (PMID 35741162, 2022). "The reported incidence of clinically evident IL-2 related myocarditis varies considerably (0.6–25%), but is substantially lower than that reported at autopsy." (PMID 35741162, 2022). "We present a case of a 48-year-old female who developed myocarditis and near fatal arrhythmias during high dose Il-2 therapy for metastatic renal cancer." (PMID 29399586, 2018). "Of note, myocarditis was reported in 9 patients, all occurring during IL-2 administration and requiring termination of IL-2 therapy." (PMID 29254506, 2017). "This diagnosis was evaluated in all cases based on enzyme release (laboratory evaluation), and in 7, there were no clinical, ECG, or echocardiogram findings, consistent with IL-2-mediated myocarditis." (PMID 29254506, 2017). "If concerns exist regarding myocarditis or ischemia, then cardiac enzymes or troponin should be monitored at least daily and IL-2 discontinued if confirmed." (PMID 31546315, 2014). "High levels of cytokines such as IL-2, IFN-y, TNF, IL-1, and IL-6 have been linked to myocarditis." (PMID 37941006, 2023). "Another study also revealed that Icariin could downregulate the mRNA levels of TNF-α, ICAM-1, IL-2, and IL-6, which attenuates myocardial inflammation." (PMID 36984421, 2023). "Studies have shown that 6 out of 8 patients with high IL-2 levels had myocarditis." (PMID 37941006, 2023). "IL2-induced myocarditis, a relatively common reason for discontinuing IL-2 therapy, is clinically evident in up to approximately 25% of patients, however autopsy data suggest it may occur more frequently and can lead onto chronic myocardial fibrosis." (PMID 35741162, 2022). "The patients with myocarditis also showed high levels of IL-1 receptor antagonist (interleukin 1), IL-5, and IL-16 but no proinflammatory cytokines, for example, IL-6, tumor necrosis factor, IL-1B, IL-2 or interferon-γ." (PMID 36498573, 2022). "Thus, the more likely scenario is myocarditis because of IL-2 therapy, although exacerbation of a preexisting cardiomyopathy cannot be completely ruled out without prior cardiac studies." (PMID 29399586, 2018).
myocarditis (continued). "A diagnosis of myocarditis should prompt discontinuation of that cycle of IL-2, but if LVEF returns to baseline, patients may cautiously proceed with additional cycles of HD IL-2, usually without recurrence of this side effect." (PMID 31546315, 2014). "Both human KD patients and LCWE-treated mice developed coronary arteritis, myocarditis, valvulitis, and pericarditis, as well as elevated plasma levels of interleukin (IL)-2, IL-6, IL-10, monocyte chemoattractant protein (MCP)-1, and tumor necrosis factor (TNF)-α in acute phase." (PMID 22737215, 2012). "Furthermore, IL-2 can cause non-infectious myocarditis with acute troponin level, abnormal ECG, and decreased left ventricular function but normal coronary angiography." (PMID 37355743, 2023). "However, serious irAEs may occur and careful monitoring of patients receiving high dose IL-2 is always warranted, for both the acute toxicity of the treatment, and the potential for serious irAEs such as myocarditis and neurologic events." (PMID 29254506, 2017). "Th1 cells, which secrete mainly IL-2, IFN-γ and IL-12, and Th17 cells, which secrete mainly IL-17, exhibit proinflammatory properties in myocarditis." (PMID 37901475, 2023). "The evidence generated thus far suggests that DCs play a role in this scenario, as they were shown to be activated in CVB3-induced myocarditis, resulting in the stimulation of IFN-γ and IL-2 production by CD8+ T lymphocytes." (PMID 28973047, 2017). "DCs were shown to be activated upon CVB3-induced myocarditis, resulting in IFN-γ stimulation and IL-2 production by CD8+ T lymphocytes." (PMID 28973047, 2017). "Interestingly, evidence of immune mediated toxicity may be associated with response as, from our observation, 3 out of 4 patients with myocarditis, 12 (6 PR 6 CR) out of 18 patients with immune thyroiditis and 2/2 (both CR) with inflammatory arthritis responded to IL2." (PMID 27777776, 2016). "Endomycardial biopsy was nonspecific showing fibrosis with subsequent cardiac MRI showed evidence of myocardial edema, consistent with Il-2 induced myocarditis in the setting of no prior cardiac history." (PMID 29399586, 2018). "Lack of excessive IL-2, IL-6 or IFN-γ responses in our TIM-3 deficient patient highlights the view that immunological presentations in SPTCL/HLH or primary HLH are different from the myocarditis case described here." (PMID 38485795, 2024). "Our case reiterates that noninfectious myocarditis can occur after IL-2 therapy and may present similarly to an acute myocardial infarction and timely diagnosis and discontinuation of therapy is important." (PMID 29399586, 2018).
tetanus (21 papers, 2007 to 2025). A serious infectious disorder that follows wound contamination by the Gram-positive bacterium Clostridium tetani. "LASSO modeling also revealed positive association between pertussis IgG levels with CB concentrations of T-cell-derived cytokines IL-2, IL-17A, and IL-31, but in contrast to tetanus, APRIL was negatively associated with pertussis, as was IL-33." (PMID 37251388, 2023). "The recombinant tetanus vaccine group reported greater expression of IL‐2 and IFN‐γ by T‐cells than the TT vaccine group." (PMID 34081408, 2021). "In fact, in another long-term study, when human T cells, co-cultured with the other PBMC, were activated with the tetanus antigen plus IL-2, dexamethasone (10−7 M) decreased the levels of FoxP3 mRNA following long-term culture (11 days)." (PMID 30845709, 2019). "Influenza-specific IL-2+/- IFNγ+ cells were used as committed Th1 cell controls, and tetanus-specific 2+γ- cells as uncommitted Thpp cell controls." (PMID 24788814, 2014). "Tetanus also stimulated a substantial population of Tbet- IL-2- IFNγ- TNFα+ cells, consistent with stochastic expression of IL-2 in the Thpp as well as the Th1 population." (PMID 24788814, 2014). "Of note is one patient in group B, vaccinated with tetanus 4 weeks before receiving IL-2." (PMID 17428345, 2007). "T cell activation was assessed by measurement of intracellular cytokines (IL-2, IFNγ, TNFα) following stimulation of peripheral blood T cells with PHA, a tetanus and diphtheria cocktail, PPD, anti-CD3, or SEB." (PMID 39061230, 2024). "Lymphocyte proliferation was normal upon stimulation with 4 mitogens (PHA, IL-2, anti-CD3, PWM) and 3 recall antigens (candida, diphtheria, tetanus), whereas proliferation upon the predominant B cell mitogen SAC was markedly reduced." (PMID 33995346, 2021). "Lymphocyte proliferation was normal upon stimulation with the mitogens PHA, IL-2, anti-CD3, and PWM, and three recall antigens (candida, diphtheria, tetanus), whereas proliferation to the predominant B cell mitogen SAC was markedly reduced." (PMID 33995346, 2021). "Lymphocyte proliferation was normal upon stimulation with 4 mitogens (PHA, IL-2, anti-CD3, PWM) and 3 recall antigens (candida, diphtheria, tetanus), whereas proliferation upon the B cell mitogen SAC was reduced." (PMID 33995346, 2021). "The production of 9 cytokines (IFN-γ, TNF-α, IL-2, IL-4, IL-10, IL-17, IL-21, TGF-β, GM-CSF) following in vitro stimulation of PBMCs with tetanus and diphtheria toxoid was analyzed, and was found to be similar in young and elderly adults." (PMID 27602049, 2016). "In contrast a second patient received tetanus vaccination after IL-2 and did not respond." (PMID 17428345, 2007). "However, data from a 2-year old calf following routine rabies and tetanus vaccination showed that both TNF-a and IL-2 responses could be successfully quantified at this age (Edwards, unpublished), suggesting that assay sensitivity may not be limiting the ability to detect immune responses." (PMID 34793450, 2021). "In contrast to the response observed after infection, the majority of vaccine-induced CD4+ T cells had a phenotype of IL-2+TNF-α+IFN-γ- cells similar to responses observed with other non-live vaccines, such as hepatitis B or tetanus." (PMID 26465323, 2015).
atopic dermatitis (20 papers, 2014 to 2026). "Atopic dermatitis is associated with decreased lymphoproliferative responses upon stimulation with T-cell mitogens, depending on IL-2, which, in turn, upregulates the expression of its own receptor." (PMID 38672221, 2024). "The ELISA experiment confirmed that propolis reduced the levels of MMP-9 and IL-2 in UBV-induced allergic dermatitis of HSF cells in a dose-dependent manner." (PMID 40232010, 2025). "Avène spring water, as a mineralized water, has shown proliferative effects in lymphocytes isolated from atopic dermatitis (AD) patients, along with increases in Th1 cytokines (IFNγ and IL2) and reductions in Th2 cytokines." (PMID 38921545, 2024). "Interestingly, mast cell–derived IL-2 has been shown to attenuate allergic dermatitis, and therapy using IL-2 or its agonist has demonstrated a reduction in clinical symptoms of AD." (PMID 41492481, 2026). "Sleep disturbances in atopic dermatitis are not only due to sleep deprivation related to nighttime itching but also to dysregulation in the release of inflammatory mediators (IL-1b, IL-2, TNF-a, IFN-g, IL-6, IL-4, and IL-10) and neuroendocrine molecules such as cortisol and melatonin." (PMID 38731996, 2024). "Furthermore, consistent with previous reports, our studies have shown that CD4−CD8− (double negative, DN) iNKT cells protect against allergic skin inflammation in a mouse model of atopic dermatitis, accompanied by the expansion of Treg cells via increased IL2 production." (PMID 36499642, 2022). "Th2 cells release cytokines including interleukin 2 (IL-2), IL-4, as well as IL-17 and IL-22 released from Th17 and Th22 cells, which may all contribute to skin barrier disruption and the development of atopic dermatitis." (PMID 34199951, 2021). "There were 28 core targets related to UVB-induced allergic dermatitis, of which hub proteins were TNF-α, NFKB1, MMP-9, and IL-2." (PMID 40232010, 2025). "In fact, the use of a chimeric IL2/IL33 protein was shown to be protective in renal injury and monoclonal anti-IL-33 antibodies where shown to excert promising effects in the control of atopic dermatitis." (PMID 30949175, 2019).
mastitis (20 papers, 2009 to 2025). Inflammation of breast tissue during lactation or postpartum due to an obstructed duct or infection. "In order to characterize the expression of genes associated with immune response mechanisms to mastitis, we quantified the relative expression of the IL-2, IL-4, IL-6, IL-8, IL-10, IFN-γ and TNF- α genes in milk cells of healthy cows and cows with clinical mastitis." (PMID 21637453, 2009). "On one hand, they secrete cytokines to modulate the inflammatory microenvironment, particularly IFN-γ, IL-2, and IL-17, which play pivotal roles in preventing mastitis and exert direct effects on tissue and downstream adaptive immune responses." (PMID 41142813, 2025). "The SCC and levels of generated cytokines (interleukin (IL)-1, IL-2, IL-4, IL-5, IL-6, IL-8, IL-10, and IL-12) in milk increase in both naturally occurring and experimentally induced mastitis." (PMID 40303387, 2025). "The CD4+, CD8+ T cells of cows with mastitis expressed significantly higher single-cytokine (TNF-α or IL-2) than those of healthy cows." (PMID 36960295, 2023). "The significant increase in the IL-2 level in dairy cows suffering from mastitis suggests that IL-2 is a marker of the disease." (PMID 34436243, 2021). "Lactating cows with clinical mastitis and subclinical mastitis showed a marked increase in interleukin (IL)-2, IL-6, IL-1β, and tumor necrosis factor (TNF)-α." (PMID 34827839, 2021). "Recently, we have reported increased concentrations of plasma IL-2 during mastitis induced by both S. aureus and E. coli." (PMID 34235202, 2021). "In future studies, the inflammatory factors (TNFα, IL-2, IL-6), the number of S aureus in mammary gland, and the underlying mechanisms need to be detected, which may provide a theoretical basis for CTE application in the treatment of S. aureus mastitis." (PMID 41309393, 2025). "In the milk of subclinical mastitis in this study, WC1+ γδ T cells exhibited significant upregulation of IFN-γ, IL-2, TNF-α, IL-17, and GZMB." (PMID 41142813, 2025). "Specifically, in subclinical mastitis milk, the expression levels of five cytokines—IFN-γ, IL-2, TNF-α, IL-17, and GZMB—were significantly higher in WC1+ γδ T cells compared to healthy cows." (PMID 41142813, 2025). "Our study showed that the mastitis immunological profile in the mammary gland may be related to specific HMOs, as the levels of the branched hexasaccharide LNH, its disialylated derivative DSLNH, 3’SL, and DFLac were positively associated to some pro-inflammatory cytokines (IL2, IL6, IL17 and IFNγ)." (PMID 35079053, 2022). "Some positively selected genes were reported to be associated with lactation function and disease resistance, such as the butterfat rate [PPARGC1A], milk production [B4GALT1], immunity [IL2 and NFATC3], and mastitis resistance [ITSN2]." (PMID 35422847, 2022). "Both experimentally induced or naturally occurring mastitis results in an increase in the somatic cell count (SCC) and levels of produced cytokines (interleukin (IL) IL-1, IL-2, IL-4, IL-5, IL-6, IL-8, IL-10, and IL-12) in milk." (PMID 35335696, 2022). "CD25 is the main receptor for IL-2, and the higher expression of CD25 in bovine neutrophils was reported as a potential biomarker of inflammation during various diseases such as mastitis." (PMID 34235202, 2021). "They found higher serum levels of IL-1β and IL-2, TNF-α, IL-6, and IFN-γ in subclinical mastitis compared to control cows." (PMID 34484387, 2021). "In contrast to our findings, previous research showed a non-significant rise in IL-2 and IL-6 markers in cows with subclinical mastitis." (PMID 36899749, 2023). "IL-2, TNF-α, and IFN-γ have a vital role in mastitis prevention, according to bovine studies." (PMID 36960295, 2023).
mastitis (continued). "Additionally, the observed downregulation of IL-4 and IL-2 following SA infusion in SCM cows indicates that its immunomodulatory effects primarily enhance immune cell phagocytic activity rather than antibody production, which has a limited role in aiding mastitis recovery." (PMID 40564979, 2025). "No significant change in gene expression of IL-2, IL-4, IL-6, IL-8, IL-10, IFN-γ, and TNF-α by real-time PCR in milk among animals without mastitis vs. animals with mastitis was observed." (PMID 35335696, 2022). "For this purpose, the expression of the interleukin 2 (IL-2), IL-4, IL-6, IL-8, IL-10, interferon gamma (IFN-γ) and tumor necrosis factor alpha (TNF-α) genes was investigated in Black and White (BW) Holstein and Gyr cows with and without clinical signs of mastitis." (PMID 21637453, 2009).